IL22 (interleukin 22)
Diseases named in the same sentence as IL22 in open-access papers (continued):
Sharing a sentence is not in itself a finding about the gene and the disease.
intestinal infection (34 papers, 2010 to 2025). "This activation promotes the production of interleukin-22 (IL-22), enhancing the body’s defense against intestinal infections and inflammation caused by intestinal injury." (PMID 40241220, 2025). "Mice that lack ILC3 are highly susceptible to intestinal infection with C. rodentium, largely recapitulating the phenotype of IL-22-deficient mice." (PMID 27656182, 2016). "Previous studies have demonstrated the involvement of IL-22 in skin tissue defense and wound healing mechanisms, as well as its protective role in intestinal infections and liver injury." (PMID 39630234, 2025). "NoV infection can play a protective role in DSS-induced intestinal injury and murine Citrobacter-induced intestinal infection by eliciting an IFN-I response in the mouse colon to promote IL-22 production by natural lymphocytes." (PMID 35216425, 2022). "IL-18 is emerging as an IL-22-induced and epithelium-derived cytokine which contributes to host defence against intestinal infection and inflammation." (PMID 35169117, 2022). "Studies have shown that ILC3s promote protective immunity against gastrointestinal infection and opportunistic fungal pathogens by producing IL-17A and IL-22." (PMID 35844574, 2022). "I3Ald and I3LA act as AhR ligands and activate AhR, which in turn activates IL-22 expression, and IL-22 plays an important role in reducing the severity of many intestinal infections." (PMID 35606749, 2022). "For instance, IL-22 plays a beneficial role in acute intestinal infections where rapid repair of colonic epithelium is required, such as infection caused by Citrobacter rodentium." (PMID 34992594, 2021). "IL-22 is a pleiotropic cytokine with broad immunoregulatory functions during intestinal infection and inflammation." (PMID 33613532, 2020). "Citrobacter rodentium is a gastrointestinal infection that requires early IL-22 from group 3 innate lymphoid cells (ILC3) for resistance." (PMID 30723466, 2019). "Resistance to intestinal infection with C. rodentium is mediated by IL-22, and ILC3s are the predominant IL-22-producing cell population during the first week of infection." (PMID 29470558, 2018). "Whereas IL-23 was highlighted as a key regulator of mucosal immune responses following intestinal infection and inflammation including T. gondii induced ileitis, IL-22 was shown to be effective in antimicrobial defense directed against C. jejuni." (PMID 27385977, 2016). "A governing signal that drives both IL-22 and CXCL13 expression is integrated by LTβR, with LTβR initiating an ILC-DC cross talk via IL-23 to induce IL-22 following intestinal infection with Citrobacter rodentium." (PMID 27579025, 2016). "Studies in models of intestinal infection have shown that NCR−ILC3 are able to produce IFN-γ in addition to IL-22 and IL-17." (PMID 27882334, 2016). "Surprisingly however, recombinant IL-22 administration can restore TLT formation in the colon of LTβR-deficient mice, suggesting that IL-22 can directly and independently impact TLT organization during intestinal infection." (PMID 27579025, 2016). "Although the mechanisms leading to ILC activation during intestinal infection remain poorly understood, intestinal MPs and/or DCs are capable of inducing the production of IL-22 by ILC3 through IL-23 and IL-1β (refs 17, 18, 19, 20)." (PMID 26269452, 2015). "In an intestinal infection with C. rodentium, IL-22 is produced earlier than IL-17A and it plays a decisive role, whereas IL-17A does not." (PMID 23379788, 2013). "IL-22 is made by multiple cell types, and in other models of acute intestinal infection and inflammation, innate lymphoid cells appear to be the primary source of IL-22." (PMID 22624013, 2012). "IL-22 signaling is crucial in the early phase of host defense against intestinal infection." (PMID 34973084, 2022). "In addition, both IL-22 and IL-12 also induce IL-18 expression in epithelial cells during intestinal infection." (PMID 31707260, 2019).
intestinal infection (continued). "Notably, IL-22 supplementation to Ahr-deficient mice normalizes the expansion of the microbiota and reduces Th17 deviation, demonstrating that IL-22 is protective against intestinal infection." (PMID 31683543, 2019). "Accordingly, IL-22 is important to combat most intestinal infections." (PMID 25799189, 2015). "In this regard, a recent study in a murine intestinal infection model has shown that IL-22 produced by CD4+ T cells contributes to late-phase responses to an intestinal pathogen, while IL-22 produced by innate cells plays a critical role in early-phase responses." (PMID 23577040, 2013). "However, ILC3 from MyD88-deficient animals failed to upregulate the production of IL-22 and IL-17 upon intestinal infection, suggesting that MyD88-mediated signaling is strictly required for the functional activation of ILC3 after pathogenic challenge." (PMID 28520792, 2017). "ILC3s are important innate sources of IL-17A, IL-22 and IFN-γ, which play crucial roles in regulating intestinal infection and maintaining homeostasis." (PMID 39695888, 2024). "NoV infection can play a protective role in DSS-induced intestinal injury and murine Citrobacter-induced intestinal infections via inducing an IFN-I (α/β) response in the mouse colon and promoting Interleukin 22 (IL-22) production by natural lymphocytes." (PMID 35216425, 2022). "In a model of intestinal infection, CXCL16 released by DC induces the migration of ILC3 to the villus lamina propria where they respond to IL-23 and produce IL-22, which is essential for the release of antimicrobial peptides and infection control." (PMID 27882334, 2016). "Interestingly, SCFAs also promote human CD4+ T cell IL-22 production, even from IBD patients, our study provides SCFAs as a new potential therapeutic target for suppressing intestine infection and inflammation, and eventually treatment of IBD patients." (PMID 32901017, 2020). "Although IL-22 has been demonstrated to protect the host from gastrointestinal infections, the functional role of Stat3 in the epithelium has not been demonstrated." (PMID 25799189, 2015). "In murine models of intestinal infection with Citrobacter rodentium, there is greater intestinal damage in the absence of IL-22, leading to greater levels of systemic bacteria." (PMID 20211031, 2010). "Interestingly, IL-22 can have distinct and nonredundant roles in different models of intestinal infection and inflammation, probably due to specific niche localization." (PMID 37101209, 2023). "Additionally, Rag2γc mice exhibited significantly lower levels of IL-22 but not IFN-γ or IL-17A than wild-type B6 mice, suggesting that IL-22 plays a role in C. albicans gastrointestinal infection." (PMID 33488563, 2020).
breast cancer (33 papers, 2008 to 2026). A primary or metastatic malignant neoplasm involving the breast. "The association between breast cancer progression and increased IL-22 levels and ILC3s infiltrate is well determined." (PMID 36341381, 2022). "An increased expression of IL-22 in breast cancer has been found to be associated with elevated infiltration of tumor associated macrophages and poor clinical outcomes." (PMID 35295139, 2021). "Some recent studies indicated increased IL-22 level was associated with progression of breast cancer." (PMID 32649314, 2020). "Here, using an IL‐22 knockout breast cancer mouse model, we have explored the cancer cell malignancy‐associated role of IL‐22 in breast cancer pathogenesis." (PMID 31725949, 2020). "In our present study, we analyzed the potential role of the IL-22 axis in the association between aggressive MDA-MB-231 breast cancer cells and the bone environment, particularly in relation to MSCs and macrophages." (PMID 31935914, 2020). "Clinically, in human breast tumor tissues, increased number of IL‐22+ cells in the TME is associated with an aggressive phenotype of breast cancer." (PMID 31725949, 2020). "We show from our current analyses that the IL-22-IL-22R1-linked axis is a critical component of the invasive phenotype in aggressive breast cancer." (PMID 31935914, 2020). "In human breast tumor tissues, increased number of IL‐22+ cells in tumor microenvironment is associated with an aggressive phenotype of breast cancer." (PMID 31725949, 2020). "In conclusion, we have here elucidated a mediatory role of an IL-22-linked signal axis in metastatic breast cancer cells and uncovered mechanisms underlying the potential crosstalk of cancer cells with host cells within the local tumor environment." (PMID 31935914, 2020). "The pathological functions of this IL-22-linked axis may be a promising therapeutic target for breast cancer bone metastases." (PMID 31935914, 2020). "Increased interleukin-22 (IL-22) level was reported to associate with progression of breast cancer." (PMID 32649314, 2020). "Similarly, IL‐22 has been associated with in vitro transformation and migration of breast cancer cells." (PMID 31725949, 2020). "Moreover, IL-22 has been implicated in cancer development and progression including colon cancer and breast cancer." (PMID 35295139, 2021). "Future research involving larger, well-balanced cohorts and multicentre collaboration is necessary to validate the potential role of IL-21 and IL-22 as biomarkers and to better understand their involvement in the breast cancer pathogenesis." (PMID 40729006, 2025). "The study involved 60 women with breast cancer and 20 women with benign breast lesions, and the analysis of IL-21 and IL-22 protein concentrations was performed using the enzyme-linked immunosorbent assay (ELISA) method." (PMID 40729006, 2025). "We plan to conduct multicentre studies in the future to improve the statistical reliability and ensure a more representative patient group for the evaluation of IL-21 and IL-22 as potential immune markers in breast cancer." (PMID 40729006, 2025). "According to miRDB, one of the targets of miR‐4708‐3p is interleukin 22, which has been previously reported to be involved in chemotherapy resistance in lung and breast cancers." (PMID 39587714, 2024). "IL-22 stimulates breast cancer cell proliferation via epithelial proliferation and immunosuppressive effects." (PMID 37542283, 2023). "TAMs-derived IL-6, IL-10, IL-22, and IL-23, together with T-lymphocyte-derived IL-9, IL-10, IL-37, and IL-35 and other cytokines, regulate the immune microenvironment of breast cancer tumors." (PMID 37542283, 2023). "Specifically in mammary carcinoma, IL-22, a cytokine produced in large quantities by Th22, has been shown to exacerbate tumor growth." (PMID 36142210, 2022). "Previous studies have reported that ILs such as IL-17A, IL-22, and IL-33 promote neoplastic cell transformation and breast cancer tumorigenesis." (PMID 33800170, 2021).
breast cancer (continued). "A recent study has identified T‐helper cell types‐1, ‐17 and ‐22 (Th1, Th17, and Th22) cells as primary source and CD11b+ cells as a contributing source of IL‐22 in breast cancer TME." (PMID 31725949, 2020). "Others reported breast cancer cell-derived IL-1α up-regulated IL-22 production of T cells in an AhR- and RORγt-dependent manner, which indicated a direct crosstalk between cancer cells and immune cells." (PMID 32649314, 2020). "In human breast tumors, the number of IL‐22+ cells positively correlates with the aggressive phenotype of breast cancer." (PMID 31725949, 2020). "This correlation of IL‐22 levels with invasion was confirmed in human breast cancer where the number of IL‐22‐positive cells positively correlated with the invasiveness of breast cancer." (PMID 31725949, 2020). "For this, we used breast carcinoma progression TMA to evaluate IL‐22 levels in different stages of breast cancer progression." (PMID 31725949, 2020). "Our data on human breast cancer where increased number of IL‐22+ cells correlated with invasiveness of cancer also suggest that the presence of IL‐22 in the TME is important for the cancer cell invasion." (PMID 31725949, 2020). "Our study identifies a previously unrecognized malignant‐stage‐specific role of IL‐22 in breast cancer." (PMID 31725949, 2020). "In breast cancer, the role of IL‐22 has been shown in stimulating epithelial cell proliferation, transformation, and migration." (PMID 31725949, 2020). "Here, we showed that inactivation of IL‐22 gene inhibited the malignant transition stage of tumor progression that resulted in an overall inhibition in the growth and metastasis of breast cancer." (PMID 31725949, 2020). "Cohorts of female mice carrying IL‐22+/+or IL‐22+/− or IL‐22−/−PyMT genotypic combinations were monitored for mammary tumor development by whole‐mount mammary gland carmine staining." (PMID 31725949, 2020). "In breast cancer, the current knowledge of IL‐22 function is based on cell line models and little is known about how IL‐22 affects the tumor initiation, proliferation, invasion, and metastasis in the in vivo system." (PMID 31725949, 2020). "To extend our knowledge of the function of IL‐22 in breast cancer, we developed an IL‐22 knockout spontaneous breast cancer mouse model." (PMID 31725949, 2020). "Collectively, these results suggest that IL-22 enhances the invasive capacity of breast cancer cells via the induction of MMP9 expression, as well as via S1P signaling." (PMID 31935914, 2020). "To assess the impact of exogenous IL-22 on tumor growth, we applied three breast cancer models by transplanting 4T1 cells to wild type BALB/c mice and transplanting MCF7 cells and MDA-MB-231 cells to BALB/c Nude mice." (PMID 32649314, 2020). "In breast cancer, relatively few studies have been performed to understand the role of IL‐22 in disease pathogenesis." (PMID 31725949, 2020). "In this study, we showed IL-22 exerted a proliferative effect on breast cancer cells in a STAT3-dependent manner." (PMID 32649314, 2020). "The downregulation of the expression of EMT transcription factors Snail‐1, Snail‐2, Twist‐1, Zeb‐1, and MMP‐3 in IL‐22−/−PyMT tumors suggests that IL‐22 mediates invasion through the EMT pathway in breast cancer." (PMID 31725949, 2020). "Nonetheless, results from human studies are needed to confirm the correlation between IL-22 and breast cancer." (PMID 32649314, 2020). "Although the expression of IL-22 was found to be elevated in aggressive breast cancer cells, the role of this cytokine in breast cancer metastasis remained unclear." (PMID 31935914, 2020). "Collectively, our present results indicate a potential role of IL-22 in driving the metastasis of breast cancers into the bone microenvironment through the IL22R1-S1PR1 axis." (PMID 31935914, 2020).
breast cancer (continued). "The evidence to date thus indicates that IL-22 can be produced in inflammatory states and stimulate the S1P pathway, thereby accelerating the development of breast cancer metastases." (PMID 31935914, 2020). "We found IL-22 stimulated proliferation of breast cancer cells in a signal transducer and activator of transcription 3 (STAT3)-dependent manner." (PMID 32649314, 2020). "The authors also demonstrated that the IL-1 receptor antagonist anakinra abrogates IL-22 production and reduces tumor growth in a murine breast cancer model." (PMID 33613533, 2020). "In contrast to the in vivo system, recIL‐22 effectively stimulated cell proliferation in in vitro settings, which is in corroboration with earlier in vitro findings on the proliferative effects of IL‐22 on breast cancer cells." (PMID 31725949, 2020). "Here, we investigated the tumor stage‐specific function of IL‐22 in disease development by evaluating the stage‐by‐stage progression of breast cancer in an IL‐22 knockout spontaneous breast cancer mouse model." (PMID 31725949, 2020). "Infiltration of ILC3 and increased IL-22 level were reported to correlate with progression of breast cancer." (PMID 32649314, 2020). "Based on these reports and our previous findings, we studied the role of IL-22 in tumor growth of breast cancer." (PMID 32649314, 2020). "MiR-486-5p directly bound the Dock1 mRNA 3' untranslated region and inhibited IL-22-induced EMT of breast cancer cells via the Dock1/NF-κB/Snail signaling pathway." (PMID 31528235, 2019). "To identify the roles of Dock1 in IL-22-induced breast cancer cells invasion, we conducted a Transwell invasion assay." (PMID 31528235, 2019). "To determine the impact of IL-22 on invasion of breast cancer cells, we conducted a Transwell invasion assay." (PMID 31528235, 2019). "Consistent with previous findings, we also found that IL-22 promotes the metastasis and invasion of breast cancer cells." (PMID 31528235, 2019). "In this regard we are presently investigating the regulation of factors such as IL-6, IL-8 and IL-22 in breast cancer cells treated with IL-17." (PMID 19014637, 2008). "Th17 cells intervene in breast cancer and create an inflammatory environment through the production of cytokines, including IL-22, which could help fight tumor development." (PMID 41596472, 2026). "IL-22 is involved in breast cancer cell proliferation, which is a STAT3-dependent effect." (PMID 41596472, 2026). "Interestingly, a most recent study uncovered that T cell-derived IL-22 can confer breast cancer cell resistance to NK cell-meditated lysis and thereby induce immune escape, causing lung metastasis." (PMID 38596684, 2024). "In addition, using a 4T1 breast cancer model, the authors demonstrated that ILC3s are a major source of IL-22 promoted by IL-1β and IL-23." (PMID 36341381, 2022). "Interestingly, in our previous report, the PIN1 inhibitor juglone suppressed the IL-22-induced tumorigenic potential of human breast cancer MCF7 cells via MAPK signaling." (PMID 35954317, 2022). "The influence of IL-22 on hyperplasia, adenoma, early carcinoma, and late carcinoma stages of cancer was investigated using IL-22−/−/MMTV-PyMT spontaneous breast cancer mouse model showing that it is necessary for malignant transformation of cancer cells which is the critical stage for metastasis." (PMID 33042126, 2020). "This study identifies tumor stage‐specific function of interleukin (IL)‐22 in breast cancer." (PMID 31725949, 2020). "In conclusion, we confirm the proliferative effect of IL-22 in breast cancer." (PMID 32649314, 2020). "IL-22 has been suggested to regulate the progression of several tumors but its involvement in breast cancer metastasis is largely unknown." (PMID 31935914, 2020). "However, the correlation between IL-22 level and receptor type of tumor cell is unclear in human breast cancer." (PMID 32649314, 2020).